TMPPE (transmembrane protein with metallophosphoesterase domain)
Synonyms: FLJ45032
Tractability: Antibody: UniProt predicts a signal peptide or a membrane-spanning region. PROTAC: its protein half-life has been measured.
Gene: Protein-coding gene on chromosome 3 (33,090,421 to 33,097,146, reverse strand). Ensembl gene ENSG00000188167.
Subcellular location: Membrane
Subcellular location (Human Protein Atlas): Mitochondria; Nucleoplasm
Gene Ontology:
Molecular function: protein binding; hydrolase activity
Cellular component: membrane
Genetic constraint (gnomAD): Loss-of-function variants: 17 observed, 24.27 expected, observed/expected ratio (o/e) 0.7, 90% interval 0.48 to 1.05. The upper end of that interval is the gene's LOEUF score, 1.05, which puts it in group 4 of 6, group 1 being the genes least tolerant of losing a copy. Missense variants: 526 observed, 614.78 expected, observed/expected ratio (o/e) 0.86, 90% interval 0.8 to 0.92. Synonymous variants: 240 observed, 258.34 expected, observed/expected ratio (o/e) 0.93, 90% interval 0.83 to 1.03.
Homologues: Orthologues: macaque TMPPE (95% identical), dog TMPPE (87% identical), guinea pig TMPPE (86% identical), rat Tmppe (85% identical), mouse Tmppe (85% identical), pig TMPPE (72% identical), zebrafish tmppe (51% identical), Caenorhabditis elegans F40B5.2 (32% identical), Caenorhabditis elegans T23G7.2 (26% identical).
Diseases named in the same sentence as TMPPE in open-access papers:
TMPPE is named in the same sentence as 3 diseases in open-access papers, as found by Europe PMC text mining. Sharing a sentence is not in itself a finding about the gene and the disease. The quoted sentences say what the papers report.
diabetes (1 paper, 2019). "Several other genes displaying inverted correlations have previously been linked to diabetes (7/18), either by functional studies (TRIB1, glucose metabolism; NFKBIA, insulin resistance pathway) or as candidate disease genes in GWAS or gene expression studies (TMPPE, PRTG, and ZNF319)." (PMID 31159854, 2019).
major depressive disorder (1 paper, 2024). An episode of depression lasting two or more weeks without an intervening episode of mania. "For example, a GWAS of major depressive disorder stratified by sex in two large biobanks, Generation Scotland and UK Biobank, found that the genes CRTAP, GLB1, and TMPPE at chromosome 3p22.3 were significantly associated with major depressive disorder in males, but not in females." (PMID 38790194, 2024).
TMPPE also shares sentences with these, for which no sentence is quoted: thalassemia (1 paper).